CTNNB1 (catenin beta 1)
Diseases named in the same sentence as CTNNB1 in open-access papers (continued):
Sharing a sentence is not in itself a finding about the gene and the disease.
tumor (continued). "Several gene alterations in predisposing loci have been well-identified, including mutations in Wilms' tumor gene 1 (WT1), catenin beta 1 (CTNNB1), insulin-like growth factor-2 (IGF2) and Wilms' tumor gene on the X chromosome (WTX)." (PMID 32318341, 2020). "Analysis of HCC patient RNA-seq expression data from The Cancer Genome Atlas (TCGA) project indicated increased CTNNB1 expression in tumor compared to normal liver tissue." (PMID 33222692, 2020). "In the case of Wilms11, three tumor explants were cultured separately and all three were wild type for CTNNB1 (right)." (PMID 33379206, 2020). "In Wilms3 the tumor carried a p.T41A CTNNB1, an amino acid that is also a target for phosphorylation by GSK3β, and the Wilms11 tumor carried a p.S45F mutation." (PMID 33379206, 2020). "Expression of the canonical skeletal muscle WNT agonist Wnt5a (WNT5A), canonical WNT receptor Fzd1 (FZD1), and β‐catenin itself (CTNNB1) was all reduced with C‐26 tumor burden, whereas the negative regulator of β‐catenin, GSK3B, was up‐regulated." (PMID 31930715, 2020). "The G4 subtype contains various tumor types with mutations in TCF1, while G5 and G6 are strongly correlated to mutations in CTNNB1, leading to activation of the Wnt/β-catenin pathway." (PMID 32443599, 2020). "CSNK1A1 inhibits the canonical Wnt/β-catenin signaling pathway by promoting the degradation of CTNNB1, thereby promoting tumor cell growth." (PMID 32993576, 2020). "SOX30 can inhibit tumor-metastasis by directly binding to CTNNB1 promoter and result in a favorable prognosis." (PMID 31488089, 2019). "In this study, it was found that the expression of CTNNB1 in tumor tissues was significantly higher than that in normal tissues, and the survival period of patients with high expression of CTNNB1 was significantly shortened." (PMID 32038705, 2019). "An in vivo tumor regression study showed a significant reduction in the tumor burden on all the days of measurement after the first dose of treatment for CTNNB1-CA delivery." (PMID 31269666, 2019). "It is reported that abnormal accumulation of β-catenin contributes to most cancers and repressed CTNNB1 also leads to inducing apoptosis in some tumor cells." (PMID 31001122, 2019). "We found that 60% (18/30) of samples with high PLK1 expression (above median PLK1 TPM of all tumor samples) also had high β-catenin (CTNNB1) expression (above median CTNNB1 TPM of all tumor samples)." (PMID 31741706, 2019). "Novel interstitial deletions in CTNNB1 spanning intron 1 to exon 3/intron 3 were also found in 7.7% (4/52) of the tumours." (PMID 29872083, 2018). "In early-stage ADC patients, the elevated SOX30 represses Wnt/CTNNB1-signaling by directly binding to CTNNB1 promoter to inhibit tumor-metastasis and results in a favorable prognosis of these patients." (PMID 30514297, 2018). "Among three analyzed tumor-related genes, CTNNB1 and MET act as the oncogenes in HCC, and CCND1 is the hallmarker of cell cycle procession." (PMID 30327605, 2018). "Median age at operation and tumour size for the group of tumours with APC/CTNNB1/ZNRF3 alterations were 52.5 years and 10 cm respectively and were not significantly different from those without mutations (46 yrs, p = 0.3517, and 10 cm, p = 0.5731)." (PMID 29872083, 2018). "It has been widely reported that PI3K/AKT/mTOR, MAPK, and WNT/CTNNB1 pathways all play major roles in MPNST tumor initiation and progression." (PMID 30112810, 2018).
tumor (continued). "The allelic frequencies of mutant CTNNB1 significantly correlated with the estimated histological tumour content (r = 0.88, p = 6.61 × 10−8) and were consistent with the presence of a heterozygous mutation within all tumour cells [Suppl." (PMID 29541918, 2018). "From the data of our present study, the reason is that SOX30 plays different roles on tumor metastasis as differently direct regulation of CTNNB1." (PMID 30514297, 2018). "Amongst 16 CTNNB1 wildtype tumours with the presence of nuclear accumulation, five harboured ZNRF3 deletion and one harboured APC mutation." (PMID 29872083, 2018). "The present study proposed a mechanism for disease progression in which combined CTNNB1 missense mutation p.Ser33Phe and MED12 frameshift mutation p.Tyr1278fs promote tumor progression in MPNST." (PMID 29369179, 2018). "In early-stage ADC patients, elevated SOX30 expression inhibits tumor-metastasis by directly binding to CTNNB1 promoter resulting in a favorable prognosis of these patients." (PMID 30514297, 2018). "Our results demonstrate that β-catenin /CTNNB1 plays important role in tumor initiation and promotion by stimulating tumor cell proliferation." (PMID 30513115, 2018). "The median overall survival rate for patients with a tumour harbouring APC/CTNNB1/ZNRF3 alteration was significantly lower compared to the ones without (43 vs 114 months, log rank p = 0.0141)." (PMID 29872083, 2018). "Mutations of CTNNB1, APC and FBXW7 were detected in 9 (10.5%), 20 (23.2%), and 17 (19.8%) tumor samples, respectively." (PMID 29402328, 2018). "In our study, the association was even more evident in the group of patients with tumour harbouring alterations in APC/CTNNB1/ZNRF3." (PMID 29872083, 2018). "Additional mutations, such as P3K3CA, CTNNB1, and NF1, can be found in a subset of tumor clones (subclones), and these mutations are considered branch driver mutations that facilitate branched evolution of tumor clones." (PMID 29594039, 2018). "Out of the four tumours harbouring a CTNNB1 ∆(2 + 3) deletion, two harboured gain and one harboured cnLOH." (PMID 29872083, 2018). "Gene sets associated with activated WNT/CTNNB1 signaling, a pathway important to other types of adenocarcinomas, are elevated in expression in the HPV-inactive tumor class (Hallmark_WNT_beta_catenin_signaling–h.all.v5.1)." (PMID 28077784, 2017). "The expressions of CDH1 and CTNNB1 were significantly weaker in tumour tissue than normal bronchial epithelial cells." (PMID 29115924, 2017). "DMS were mapped to genes including pyruvate kinase, muscle (Pkm), β-catenin (Ctnnb1), and fibroblast growth factor 3 (Fgf3) that are known to be involved in tumor development including OSCC." (PMID 29073177, 2017). "Although the evidence for CTNNB1 mutation being a late event is inconsistent, these studies, and others (Refs 34, 35) clearly demonstrate that WT1 mutation can follow the 2-hit tumour suppressor model for the development of cancer." (PMID 28716159, 2017). "In our molecular analysis, we detected and verified mutations in genes such as ARID1A, CTNNB1, PIK3CA, and PTEN which are frequently affected in these tumour entities." (PMID 28103826, 2017). "APC is a tumor suppressor which promotes rapid degradation of CTNNB1 and participates in Wnt signaling as a negative regulator." (PMID 28415609, 2017).
tumor (continued). "For instance, USP9x, a deubiquitinase, and connected with CTNNB1 as shown in the network, has been reported to be required for PKCβ kinase activity and induced the cell survival and tumor-promoting activities of Notch signaling in cancer." (PMID 28054945, 2017). "Numerous studies indicate that Wnt–CTNNB1 signaling contributes to cancer progression through the maintenance of highly tumorigenic tumor-initiating cells." (PMID 28831115, 2017). "Mutational analysis of CTNNB1 and BRAF was performed in 110 and 112 human CP tumor samples respectively." (PMID 26927026, 2016). "We have recently reported that the upregulation of WNT7A (uniquely among 19 WNT ligands) results in accelerated development and progression of ovarian cancer (OvCa), and plays a critical role in tumor progression mediated by the WNT7A/CTNNB1 signaling pathway." (PMID 27195958, 2016). "Stabilizing mutations in the CTNNB1 gene increase the activity of the finely tuned WNT signaling pathway, leading to tumor formation." (PMID 26815163, 2016). "The current HCA classification scheme is based on the tumor’s morphologic and immunohistochemical characteristics and was originally validated with CTNNB1 and HNF1A gene sequencing." (PMID 26961851, 2016). "The average tumor volume of the CTNNB1 knockdown group was significantly smaller than those from the control group, which showed that the tumor formation was suppressed in the cisplatin-treated group with CTNNB1 knockdown." (PMID 27529071, 2016). "The RT-PCR results suggested that FOXO3 was highly downregulated in tumor cells, yet CTNNB1 was remarkable upregulated in tumor cell." (PMID 26915315, 2016). "In the tumor tissue there was a weak positive correlation of RACGAP1 gene expression with CTNNB1 (r = 0.288, P = 0.033), as well as an inverse association with CDKN1A gene expression (r = −0.357, P = 0.012)." (PMID 26778597, 2016). "On the other hand, the transcriptional regulation of CTNNB1 in normal cells was controlled by some other factors and different from that of tumor cells." (PMID 26915315, 2016). "After induction of aberrant Wnt activation by Ctnnb1 deletion at embryonic day 14, such mice developed tumor-like lesions in upper parts of the nasal cavity." (PMID 27902722, 2016). "During the survival analyses of Ctnnb1 mutant mice, we observed that homozygous Pygo2 knockout animals survived the initial phase of tumor initiation for up to ten weeks after induction." (PMID 27811361, 2016). "In contrast, mammary gland tumorigenesis was enhanced in Apc1638NCtnnb1+/- mice, perhaps because Ctnnb1 functions as a tumor suppressor gene in the mammary gland tumors via β-catenin’s role in E-cadherin-dependent tumor suppression." (PMID 26528816, 2015). "Although Wnt/β-catenin signaling is known to be aberrantly activated in PDAC, mutations of CTNNB1, APC or other pathway components are rare in this tumor type, suggesting alternative mechanisms for Wnt/β-catenin activation." (PMID 25747895, 2015). "(2009) revealed the presence of different CTNNB1 mutations inside and outside the clusters in 50% of the human ACP analysed, suggesting the existence of tumour heterogeneity as described in mouse ACP." (PMID 25611703, 2015). "Sufficient DNA was available on 16/19 MLLT1-mutant tumours to perform mutation analysis for WT1, CTNNB1, WTX, DROSHA, DGCR8, and SIX1/2 and this revealed five CTNNB1 mutations, one WTX mutation, and no WT1 DROSHA, DGCR8, or SIX1/2 mutations." (PMID 26635203, 2015). "NGS performed on a tumor sample from a liver biopsy obtained at the time of diagnosis revealed NF1 mutation R1241*, BAP1 truncation (exon 12), and CTNNB1 mutation N387K." (PMID 24931142, 2014).
tumor (continued). "Both CTNNB1 (58% vs. 16%) and AXIN1 (54% vs. 16%) mutations were significantly enriched in patients undergoing a subsequent recurrence of their tumor (P = 0.0045 and P = 0.0022, respectively)." (PMID 25502816, 2014). "This indicated that the function of CTNNB1 was to modulate the activity of the WNT signaling pathway, and implicated its role in stem cell-derived tumor initiation and progression." (PMID 24465727, 2014). "NGS performed on a tumor sample from the chest wall biopsy obtained at the time of diagnosis revealed PIK3CA mutation H1047R, CTNNB1 mutation S37C, and protein tyrosine phosphatase delta (PTPRD) mutation S1845fs*2." (PMID 24931142, 2014). "Here, enhanced expression of CTNNB1 and increased expression target genes accompanied with more serious transformation in hESCs implied its role in stem cell-derived tumor initiation and progression." (PMID 24465727, 2014). "NGS of a tumor sample obtained from a bone biopsy performed at the time of diagnosis revealed CTNNA1 mutation K889* and CTNNB1 mutation T41A." (PMID 24931142, 2014). "CTNNB1 and CDH1 are crucial components of cell-cell adhesion complexes, and their loss has often been associated with tumor metastasis and poor clinical outcome." (PMID 24971456, 2014). "NGS of a tumor sample obtained from a liver biopsy performed at the time of diagnosis revealed CDKN2A mutation H83Y and CTNNB1 mutation T41A." (PMID 24931142, 2014). "We also highlight some potential coordinating tumor suppressors and oncogenes for the CTNNB1 mutant tumors." (PMID 24798046, 2014). "CTNNB1 (β-catenin gene) and CDH1 (E-cadherin gene) are crucial components of cell-cell adhesion complexes and their loss has been associated with tumor metastasis and poor clinical outcome." (PMID 24971456, 2014). "Tumor tissues were tested for HER2-status and mutations in the PTEN, PIK3CA, AKT1, CTNNB1, and E-cadherin type 1 genes." (PMID 23930209, 2013). "β-catenin (CTNNB1), for instance, complexes with N-cadherin to coordinate tumor invasiveness and shows some promise as a prognostic marker." (PMID 24068912, 2013). "In vivo, on established tumor xenografts in athymic nude mice, 9 days of β-catenin silencing resulted in a significant reduction of CTNNB1 and AXIN2 expression." (PMID 23409032, 2013). "With the exception of CTNNB1, a tumor with an alteration in one of these genes rarely has a mutation in one of the other genes." (PMID 22536370, 2012). "The gene expression profiling of the 63 tumours of patients with TRG2 showed, that high expression levels of GSK3B, DNMT1 and CTNNB1 were significantly associated with better survival (conditional inference test: p = 0.006, 0.041, and 0.043, respectively)." (PMID 22970250, 2012). "Only one tumor had two mutations (NRAS Q61L and CTNNB1 45P), while all other mutations were mutually exclusive." (PMID 22536370, 2012). "The primary tumour and the established HC-AFW1 cell line were also screened for point mutations or deletions in exon 3 of the CTNNB1 gene encoding β-Catenin." (PMID 22666492, 2012). "APC is a tumour suppressor known to activate CTNNB1 and wnt pathway signalling, amongst other effects." (PMID 21781349, 2011). "Although Wnt signaling is aberrantly activated in PDAC, mutations of CTNNB1, APC or other pathway components are rare in this tumor type suggesting alternative mechanisms for Wnt activation." (PMID 21811562, 2011). "Statistical analysis shows a significant correlation between nuclear accumulation of tyrosine-phosphorylated β-catenin and HB tumours with wild-type CTNNB1 (P-value = 0.015)." (PMID 21992464, 2011). "The results reflected those seen in HB tumours with c-Met activated β-catenin found only in the cell line with wild type CTNNB1 following HGF treatment." (PMID 21992464, 2011).
tumor (continued). "High CTNNB1 nuclear staining was seen for three tumours and focal high CTNNB1 nuclear staining was seen for two tumours." (PMID 19293793, 2009). "Significance was achieved when high CTNNB1 nuclear tumours were compared with low CTNNB1 nuclear tumours, but was limited by the very small number of samples included in the analysis." (PMID 19293793, 2009). "Although not statistically significant, survival analysis in the CNS PNET cohort suggested a trend towards a better prognosis for patients whose tumours displayed high CTNNB1 nuclear staining." (PMID 19293793, 2009). "Of the 10 tumours with nuclear CTNNB1, eight (80%) displayed CCND1 overexpression, which included all tumours with high CTNNB1 nuclear positivity." (PMID 19293793, 2009). "This included 3 out of 10 (30%) tumours with CTNNB1 nuclear staining, one with low and two with a high level of staining." (PMID 19293793, 2009). "Six recurrent tumours were analysed, three with high CTNNB1 nuclear staining and three with CTNNB1 cytoplasmic staining." (PMID 19293793, 2009). "Mutations at the phosphorylation sites (codons 31, 33, 37, and 45) in the CTNNB1 gene were observed in tumours from only 5/464 patients." (PMID 16356174, 2005). "Significant negative bias was observed against most Ctnnb1 mutations (except I35 mutations) in KrasG12D-rescued conditional transformants, with these mutations largely absent from tumours rescued 30 days after ENU treatment." (PMID 41339549, 2026). "Furthermore, mutation and CNV analyses revealed frequent genomic alterations in these genes, especially COL4A1 and CTNNB1, reinforcing their potential as drivers of tumor evolution." (PMID 41291892, 2025). "There is some concordance between TERTp and CTNNB1 mutations in HCC, suggesting a potential cooperative role in hepatocarcinogenesis, as studies indicate their co-occurrence may contribute to tumor development and progression." (PMID 40243493, 2025). "CTNNB1 gain-of-function (GOF) mutations promote MMP9 secretion in the TME of HCC, inhibiting the activity of CD8+ T cells and leading to the immune escape of tumour cells and resistance to anti-PD-1 therapy." (PMID 41142820, 2025). "In addition, in mouse tumor cell lines Ctnnb1 (murine gene symbol for β-catenin) was stably expressed, and MC38 cells were subsequently used as in vivo model in this work." (PMID 39744434, 2025). "Within the intricate tumor microenvironment, when perturbations arise in cell-cell interactions and purine metabolic processes, the expression profiles and functional activities of CTNNB1 and LEF1 are prone to undergo alterations." (PMID 40236698, 2025). "Circulating tumor DNA (ctDNA) reflects the mutational landscape of tumor tissues and has been shown to reliably detect various HCC-related mutations, including those in TERT and CTNNB1 35,36." (PMID 40765562, 2025). "Functional assays confirmed that TIM-3 levels (as experimentally reduced or augmented) positively correlated with stemness features in 4T07 cells, including sphere-forming capacity and in vivo tumor formation, at least in some assays in a catenin beta 1 (CTNNB1)-dependent manner." (PMID 40859036, 2025). "The single tumor that lacked FGFR2 mutations harbored a CTNNB1 p.I35T variant and showed more favorable histologic features." (PMID 40906279, 2025).